LGI1 (leucine rich glioma inactivated 1)
Diseases named in the same sentence as LGI1 in open-access papers (continued):
Sharing a sentence is not in itself a finding about the gene and the disease.
encephalitis (continued). "The volcano and scatter plots indicated the differences in exo-miRNAs between LGI1 encephalitis cases and HDs." (PMID 37644514, 2023). "The antibody of anti-LGI1 encephalitis is IgG antibody targeting leucine-rich glioma-inactivated 1 (LGI1) protein (an extracellular component of the voltage-gated Kv1 potassium channel-complex)." (PMID 37090723, 2023). "Circos plots were applied to show the distribution of methylated CpG, CHG, and CHH sites on the chromosomes of patients with LGI1 encephalitis and HDs." (PMID 37644514, 2023). "Mechanically, miR-2467-5p significantly induced reduced expression of CSF3 and PDCD1 by binding with their 3`UTR while enhanced CCL15 expression, but not significantly correlated with peripheral blood CD19 + B cell proportion of LGI1 encephalitis patients." (PMID 37644514, 2023). "It has been reported that in patients with anti-LGI1 encephalitis, 18F-FDG PET uptake is asymmetrical in the basal ganglia and hippocampus." (PMID 37064193, 2023). "Based on these findings, he was diagnosed with anti-LGI1 encephalitis and was treated with methylprednisolone of 500mg for 5 days, with a decrement by half every 3 days, followed by oral prednisone." (PMID 37304289, 2023). "Anti-LGI1 encephalitis is characterized by cognitive impairment or rapid progressive dementia, psychiatric disorders, epileptic seizures, faciobrachial dystonic seizures (FBDS), and refractory hyponatremia." (PMID 37304289, 2023). "Seizures, especially focal seizures, are common symptoms of anti-LGI1 encephalitis in both pediatric and adult age." (PMID 37179544, 2023). "Previous studies on anti-LGI1 encephalitis using 18F-FDG PET have mainly focused on the metabolic alterations occurring within entire cerebral lobes (temporal, parietal, or frontal lobe), deep nuclei, or the hippocampus." (PMID 37064193, 2023). "Of the 14 patients with positive antibodies only in the serum, 12 had high antibody titres (>1:32), whereas the antibody titres of the other 2 patients were 1:10, including one with anti-LGI1 encephalitis and one with anti-CASPR2 encephalitis." (PMID 38152405, 2023). "Among the subtypes, the intensive care unit (ICU) admission rate of anti-GABABR encephalitis was the highest (20%) and that of anti-LGI1 encephalitis was the lowest (3.6%)." (PMID 38152405, 2023). "Taken together, we uncovered a substantial number of hypermethylation/hypomethylation events pre-marked by the poised promoter and exosome-derived microRNA profiles in LGI1 encephalitis." (PMID 37644514, 2023). "Asymmetric uptake within the hippocampus and basal ganglia was previously found in patients with anti-LGI1 encephalitis." (PMID 37064193, 2023). "Consistent with the literature in children, when acute onset seizures are the solitary symptom of anti-LGI1 encephalitis, the seizures are well controlled after timely treatment." (PMID 37179544, 2023). "The female ratio with anti-LGI1 encephalitis was 3.6%, which was significantly lower than that of the other subtypes (p<0.001)." (PMID 38152405, 2023). "The present study showed that the method using axial image slices achieved a good performance in the classification between patients with LGI1 antibody encephalitis and those with GABAB receptor antibody encephalitis." (PMID 37592180, 2023). "This abnormal pattern of weakness in the patients with anti-LGI1 encephalitis lasted for several seconds every time and occurred hundreds of times per day." (PMID 37304289, 2023). "Anti-LGI1 encephalitis and anti-CASPR2 encephalitis had a higher percentage of patients with movement disorders compared to other subtypes." (PMID 38152405, 2023). "RRBS was used to assess the genome-wide methylation patterns of PBMCs from the patients with LGI1 encephalitis." (PMID 37644514, 2023). "In nine patients with facio-brachial seizures in LGI1-antibody encephalitis, only putamen hypermetabolism was found." (PMID 36702928, 2023).
encephalitis (continued). "The main clinical features of anti-LGI1 encephalitis are seizures, particularly faciobrachial dystonic seizures (FBDS), cognitive impairment, memory disturbance, hyponatremia and neuropsychiatric disorders." (PMID 37391712, 2023). "In clinical practice, the clinical diagnosis of anti-LGI1 encephalitis mainly relies on clinical symptoms, antibody testing, and magnetic resonance imaging (MRI)." (PMID 37064193, 2023). "This study aims to discriminate between leucine-rich glioma-inactivated 1 (LGI1) antibody encephalitis and gamma-aminobutyric acid B (GABAB) receptor antibody encephalitis using a convolutional neural network (CNN) model." (PMID 37592180, 2023). "As anti-LGI1 AE has similar clinical presentations as viral encephalitis, Hashimoto's encephalopathy, other forms of autoimmune encephalitis, and rapidly progressive dementia (such as Creutzfeldt-Jakob disease), differential diagnosis is important." (PMID 40217477, 2023). "There is some evidence from a post-mortem study for complement-mediated neuronal toxicity in anti-CASPR2 and anti-LGI1 encephalitis." (PMID 35060089, 2022). "This study aims to detect the invisible metabolic abnormality in PET images of patients with anti-leucine-rich glioma-inactivated 1 (LGI1) encephalitis using a multivariate cross-classification method." (PMID 35711267, 2022). "In this study, there were 4 cases of anti-LGI1 encephalitis, and the patients with such encephalitis usually showed typical symptoms of borderline encephalitis, such as severe short-range memory deficits and psychiatric symptoms." (PMID 35126787, 2022). "Further work will include as many as possible patients with anti-LGI1 encephalitis, particularly the data from multiple institutes to improve the performance of the classifier." (PMID 35711267, 2022). "The present study, that patients with anti-LGI1 encephalitis had elevated serum and CSF CHI3L1 levels." (PMID 36685530, 2022). "Anti-leucine-rich glioma inactivated protein 1 (LGI1) encephalitis is the second most common autoimmune encephalitis (AE)." (PMID 36316880, 2022). "CHI3L1 levels in CSF and serum were highly elevated in patients with anti-LGI1 encephalitis at admission compared those with the controls.(At admission, patients with anti-LGI1 encephalitis had elevated CHI3L1 levels in the CSF and serum)." (PMID 36685530, 2022). "Patients with anti-LGI1 encephalitis were less likely to require admission to the ICU than those with anti-NMDAR or anti-GABABR encephalitis (60.0% vs. 13.9% vs. 66.7%, respectively; p < 0.001)." (PMID 35320933, 2022). "Anti-Leucine-Rich glioma-inactivated 1 (LGI1) encephalitis is an autoimmune disorder characterized by antibodies to the voltage-gated potassium channel complex (VGKC), known as limbic encephalitis, hyponatremia and faciobrachial dystonic seizures." (PMID 35896991, 2022). "The male to female ratio of patients recruited with anti-LGI1 encephalitis versus controls was 27/8 and 13/9 respectively." (PMID 36685530, 2022). "This method can improve, to some degree, the detection of invisible abnormal metabolism in the PET images of patients with anti-LGI1 encephalitis." (PMID 35711267, 2022). "This paradigm shift followed the description of LGI1-Ab encephalitis, now considered to be the most frequent form of LE, which is typically non-paraneoplastic and almost always associated with seizures." (PMID 36672553, 2022). "Anti-leucine-rich glioma-inactivated protein 1 (LGI1) encephalitis typically manifests with subtle faciobrachial dystonic or other focal seizures followed by memory disturbances." (PMID 35060089, 2022). "Only about 5% to 10% of anti-LGI1 encephalitis patients had tumors, and the most common tumor is thymoma." (PMID 36316880, 2022). "The second line of treatment (including rituximab, cyclophosphamide, mycophenolate mofetil, azathioprine, and tacrolimus) is used in a limited proportion of patients with anti-LGI-1 encephalitis." (PMID 36348436, 2022).
encephalitis (continued). "Anti-leucine-rich glioma inactivated 1(LGI1) encephalitis is one rare autoimmune encephalitis which is accompanied by inflammatory responses." (PMID 36685530, 2022). "The majority of patients with anti-LGI1 encephalitis present clinical signs of limbic encephalitis: temporal lobe epileptic seizures, memory disturbances and behavioral changes." (PMID 35453524, 2022). "Investigations about the diagnostic value of EEG have been mainly focused in anti-NMDAR and anti-LGI1 encephalitis; limited evidence is currently available on other rare forms as well as seronegative cases." (PMID 36672553, 2022). "The treatment of patients with LGI1 antibody encephalitis consists of methylprednisolone, IVIg and plasma exchange." (PMID 35453524, 2022). "For patients with HSV-1 or anti-LGI1 encephalitis two authors (LMJ and SK) extracted data from patient's electronic medical records and then completed the case report form." (PMID 36426082, 2022). "Lastly, another LGI1 encephalitis patient who had arrythmia at the time of initial presentation, presented to the emergency department at an outside hospital with syncopal episodes, followed by unexpected sudden death three days later." (PMID 36304459, 2022). "Analyzed demographics and clinical data of patients with ICI-iE, HSV-1 encephalitis and anti-LGI1 encephalitis included in this dataset are published in the related research article." (PMID 36426082, 2022). "Here, we examined in a large cohort of patients with anti-LGI1 encephalitis the performance of two indirect immunofluorescent cell-based assays (IIF-CBA) in which the LGI1 protein is expressed differently on the cell surface." (PMID 36591253, 2022). "Previous studies suggested that up to 47% of patients with anti-LGI1 encephalitis only have detectable LGI1 antibodies in serum." (PMID 36591253, 2022). "The odds of dying were 13.458 times greater in patients with anti-GABABR encephalitis than in patients with anti-LGI1 encephalitis (adjusted OR = 13.458, 95% CI = 1.270–142.631; p = 0.031)." (PMID 35320933, 2022). "Anti-LGI1 antibody encephalitis and anti-mGluR5 are both uncommon encephalitis, and we report the first case of autoimmune encephalitis (AE) with dual seropositive antibodies of leucine-rich glioma-inactivated 1 (LGI1) and mGluR5." (PMID 36316880, 2022). "Anti-LGI1 encephalitis has an annual incidence of 0.83 per million persons, and approximately 20% of patients with antibody-mediated autoimmune encephalitis are positive for anti-LGI1 antibodies." (PMID 35448972, 2022). "Anti-LGI1 antibodies were positive in both the serum and cerebrospinal fluid at approximately 2 months after symptom onset, and the patient was, therefore, diagnosed with anti-LGI1 encephalitis." (PMID 36211373, 2022). "In our study, 6 (6.98%) of 86 patients with anti LGI1 encephalitis were found to have low-T3 syndrome in the acute stage." (PMID 35222399, 2022). "In our previous study of 117 patients with anti-LGI1 encephalitis, we found that abnormal thyroid function was frequent in this group: 31.6% (37/117) showed abnormal thyroid function, and 22% of these had elevated levels of serum thyroid peroxidase antibodies." (PMID 35222399, 2022). "Accordingly, the main manifestations of our patient are FBDS and unresponsive, more similar to clinical syndrome of anti-LGI1 encephalitis." (PMID 36316880, 2022). "Phase 2 clinical trials are ongoing in patients with anti-LGI1 encephalitis (NCT04875975) and myelin oligodendrocyte glycoprotein (MOG) antibody-associated disease (NCT05063162)." (PMID 35060089, 2022). "The mortality rates were 10% for anti-NMDAR encephalitis, 2.8% for anti-LGI1 encephalitis, and 41.7% for anti-GABABR encephalitis." (PMID 35320933, 2022). "Patients with anti-GABABR encephalitis had 13.458-fold greater odds of dying than patients with anti-LGI1 encephalitis (adjusted OR = 13.458, 95% CI = 1.270–142.631; p = 0.031)." (PMID 35320933, 2022).
encephalitis (continued). "Findings in serum and CSF of patients with anti-LGI1 encephalitis and discordant results in the indicated tests." (PMID 36591253, 2022). "All patients in the anti-GABABR and anti-LGI1 encephalitis groups had abnormal MRI findings in our study." (PMID 35874583, 2022). "ICI-iE_raw_data.xlsx provides the standardized case report form with raw data of all screened patients with ICI-iE and all included patients with HSV-1 encephalitis and anti-LGI1 encephalitis." (PMID 36426082, 2022). "All anti-LGI1 encephalitis patients were treated with methylprednisolone alone or combined with intravenous immunoglobulin during phase of disease, followed by a gradual reduction of the prednisone dose." (PMID 36685530, 2022). "In anti-LGI1-encephalitis, cloning of recombinant human antibodies from the CSF of three patients indeed showed that 84% of all antibody-secreting cells and 21% of memory B cells did produce LGI1-specific antibodies." (PMID 35401530, 2022). "One study has shown that CHI3L1 levels are significantly elevated in the CSF of patients with anti-LGI1 encephalitis." (PMID 36685530, 2022). "Anti-leucine-rich glioma inactivated 1 (anti-LGI1)encephalitis is a type of rare autoimmune encephalitis." (PMID 36685530, 2022). "Seizures were more frequently, and almost exclusively, seen in anti-LGI1 (leucine-rich, glioma-inactivated 1) encephalitis, and were consisted of faciobrachial dystonic seizures (FBDS) and nonmotor focal subtle seizures." (PMID 35976312, 2022). "This cohort comprised of 40 patients with anti-NMDAR encephalitis, 24 with anti-GABABR encephalitis, and 36 with anti-LGI1 encephalitis." (PMID 35757705, 2022). "Encephalitis related to anti-LGI-1 antibody is more common than these three types, and was first described in 2010." (PMID 36348436, 2022). "Patients with LGI1 antibody encephalitis can develop mesial temporal sclerosis and hippocampal atrophy after remission of the acute phase." (PMID 35453524, 2022). "Anti-LGI1 antibody detection is important for the diagnosis of the encephalitis and prompt treatment with immunotherapy." (PMID 36591253, 2022). "It should be noted that in the same study, genus Clostridium was more abundant in anti-LGI1 encephalitis patients than in controls." (PMID 35877424, 2022). "Short-term memory loss (75.22%), faciobrachial dystonic seizures (FBDS) (52.53%), other seizures excluding FBDS (68.48%), psychiatric symptoms (57.67%), and sleep disturbances (34.30%) were the most frequently described symptoms in anti-LGI1 encephalitis." (PMID 35095736, 2022). "A previous study found that patients with anti-LGI1 encephalitis presented abnormal metabolism in the precuneus." (PMID 35711267, 2022). "(Anti-leucine-rich glioma inactivated 1 (anti-LGI1) encephalitis is an autoimmune disease mediated by inflammatory responses)." (PMID 36685530, 2022). "The anti-LGI-1 encephalitis can present with different clinicopathological features that differ in disease severity and treatment response." (PMID 36348436, 2022). "The relapse rates of anti - NMDAR, anti - GABABR and anti - LGI1 encephalitis were 25%, 33.3%, and 28.6%, respectively." (PMID 35757705, 2022). "We found that older age at onset increased the risk of death in patients with anti-NMDAR, anti-LGI1, and anti-GABABR encephalitis." (PMID 35320933, 2022). "In contrast, in this study, the independent images related to anti-LGI1 encephalitis were separated by ICA." (PMID 35711267, 2022). "Hyponatremia and faciobrachial dystonic seizures were observed in our patient with anti-LGI1 encephalitis." (PMID 35874583, 2022). "In the Netherlands, annual incidence of anti-LGI1 (leucine-rich, glioma-inactivated 1) encephalitis was 0,83 per million, similar to other neurological diseases such as Creutzfeldt-Jakob Disease and Lambert-Eaton myasthenic syndrome." (PMID 35976312, 2022). "LGI1 antibody encephalitis‐Abs is extremely rare in children and seldom presents with the phenotype reported in adults." (PMID 35015932, 2022).
encephalitis (continued). "Anti-leucine-rich glioma-inactivated 1 (LGI1) encephalitis, an autoimmune disorder, is characterized by faciobrachial dystonic seizures, epilepsy, memory deficits and altered mental status while hiccup is not commonly found in patients." (PMID 35896991, 2022). "Anti-LGI1 encephalitis mostly affects older patients of both sexes and manifests with subacute to chronic memory dysfunction and personality changes with often unrecognized epileptic syndromes, such as faciobrachial dystonic seizures." (PMID 35046526, 2022). "A recent study reported that the supplementary motor area of two patients with anti-LGI1 encephalitis presented hypometabolism in their PET images." (PMID 35711267, 2022). "There is a wide spectrum of clinical symptoms in LGI1-encephalitis, ranging from seizures (FBDS, GTCS), subacute mood and behavioral changes, cognitive disorders, and memory loss." (PMID 36348436, 2022). "A CSF sample stored at the time of the first attack was assayed and the patient was found to be LGI1-positive and CASPR-2-negative, and the diagnosis of anti-LGI1 encephalitis was made." (PMID 35448972, 2022). "The mean age of the patients with anti-LGI1 encephalitis was 61.91 ± 11.20 years, and that of the control group was 59.70 ± 11.73 years." (PMID 36685530, 2022). "The only patient with anti-LGI1 encephalitis received a combination of intravenous methylprednisolone and IVIG and recovered after treatment." (PMID 35874583, 2022). "We quantified CHI3L1 in CSF (n =30) and serum samples (n =30) from patients with anti-LGI1 encephalitis (n =35), and controls (n = 22) using an ELISA assay." (PMID 36685530, 2022). "Patients with anti-LGI1 encephalitis presenting with cognitive impairments (n = 18) had significantly higher CSF CHI3L1 levels than those without cognitive impairment symptoms (n = 12, p = 0.022), but these two groups had similar serum CHI3L1 levels." (PMID 36685530, 2022). "Of interest, it has recently been reported that higher CSF IgG4 subclass‐specific titers strongly correlated with worse outcome in anti-LGI1 encephalitis." (PMID 35757705, 2022). "A recent study also found that patients with anti-LGI1 encephalitis presented hypermetabolism in the medial temporal lobe and the basal ganglia (i.e., including the putamen and the caudate), consistent with the findings of the present study." (PMID 35711267, 2022). "In this study, we characterize the episodes of bradyarrhythmias among LGI1 encephalitis patients and evaluate LGI1 expression in cardiac tissue." (PMID 36304459, 2022). "To date, to our knowledge, no research has been conducted on the relationship between anti LGI1 encephalitis and thyroid hormone." (PMID 35222399, 2022). "Among them, anti-leucine-rich glioma inactivated 1 (LGI1) encephalitis is characterized by cognitive impairment, rapid progressive dementia, psychiatric disorders, faciobrachial dystonic seizures (FBDS), and refractory hyponatremia." (PMID 36143376, 2022). "In our study, the results demonstrated that anti-NMDAR and anti-LGI1 encephalitis were more common in patients with AE with low-T3 syndrome, accounting for 72.22% and 16.67%, respectively (< 0.005), which are consistent with previous studies." (PMID 35222399, 2022). "The mortality rates of anti-NMDAR encephalitis, anti-LGI1 encephalitis, and anti-GABABR encephalitis were 10%, 2.8%, and 41.7%, respectively." (PMID 35320933, 2022). "Observational single-center cohorts reported lower rates of rituximab use: 5/28 patients with anti-CASPR2, 3/28 patients with anti-GAD65, and 3/14 patients with anti-LGI1 encephalitis." (PMID 35060089, 2022). "Most clinical laboratories use the same commercial cell-based indirect immunofluorescence assay on transfected cells with LGI1 anchored to the cell membrane (Autoimmune Encephalitis Mosaic 6 kit; Euroimmun, Lübeck Germany)." (PMID 36591253, 2022).